CYP11B1 (cytochrome P450 family 11 subfamily B member 1)
Diseases named in the same sentence as CYP11B1 in open-access papers (continued):
Sharing a sentence is not in itself a finding about the gene and the disease.
Hypertension (continued). "The genetic polymorphisms of the CACNA1D, HLAB, CYP11B1, and LSP1 gene regions showed significant association with hypertension." (PMID 36233190, 2022). "In light of this, we propose that the differential response of variant CYP11B2, CYP11B1 and CYP17A1 genes to ACTH is an important determinant of blood pressure, tending to predispose individuals with an unfavourable genotype to hypertension." (PMID 28272372, 2017). "The genetic variants of Cyp11b1 facilitate the increased plasma 18-OH-DOC concentration in S compared with R rats, and therefore, the hypertension of S rats can be expected to have a mineralocorticoid-induced component when they consume a high-salt diet." (PMID 23130148, 2012). "In contrast, Cyp11b1 showcases an amelioration of hypertension independent of its pathogenesis, as the responsible mutations appear in normotensive Dahl salt-resistant rats (DSR)." (PMID 40332416, 2025). "In addition to the CYP11B1/CYP11B2 chimeric gene, there are some SNPs at the CYP11B1 and CYP11B2 loci that are also associated with hypertension." (PMID 35012455, 2022). "In general, in neonates with 46,XX CAH due to CYP11B1 deficiency, early glucocorticoid treatment is indicated without delay to prevent Addison crisis and hypertension." (PMID 36589846, 2022). "CYP11B1 activates the pituitary-adrenal axis by synthesizing 11β hydroxylase, promoting the accumulation of adrenal cortical hormones, and affecting the production of aldosterone, which can damage cardiac or renal organs and induce hypertension." (PMID 35831903, 2022). "The functional severity of CYP11B1 genotypes may be correlated with age at onset, degree of virilization in female, and age at hypertension." (PMID 32850530, 2020). "In this article we have summarised evidence that common functional polymorphisms exist at the CYP11B1, CYP11B2 and CYP17A1 loci, and have hypothesised that each may predispose to hypertension." (PMID 28272372, 2017). "In particular, CYP11B1 affects aldosterone and cortisol synthesis and altered regulation of the pituitary-adrenal axis at the terminal steps, which causes changes in ACTH levels and may increase the risk of hypertension." (PMID 36233190, 2022). "Cytochrome P450 family 11 subfamily B member 1 (CYP11B1 gene) is located on chromosome 8q24.3 and encodes the steroid 11 β-hydroxylase, which influences the synthesis of aldosterone and activates cellular pathways to promote hypertension and cardiovascular disease." (PMID 36532271, 2022). "Age, gender, BMI, family history of hypertension, adjusted CYP11B2 and CYP11B1 H-scores differed significantly between complete clinical success and incomplete clinical success groups." (PMID 34631800, 2021). "Variant rs7003319 in CYP11B1 3′UTR is associated with both testosterone level and high blood pressure in females, but not males." (PMID 36635277, 2023). "The unadjusted logistic regression analysis showed that age, sex, BMI and family history of hypertension were associated with complete clinical success, but adjusted CYP11B2 H-score and adjusted CYP11B1 H-score were not." (PMID 34631800, 2021).
glucocorticoid-remediable aldosteronism (12 papers, 2013 to 2025). "Familial hyperaldosteronism type I (FH type I or GRA, glucocorticoid remediable aldosteronism) is caused by a hybrid CYP11B1/CYP11B2 gene inherited as an autosomal dominant trait." (PMID 29642543, 2018). "Four forms of FH are recognized, with type I (glucocorticoid remediable aldosteronism) due to a hybrid CYP11B1/CYP11B2 gene being the most common." (PMID 39821533, 2025). "For example, glucocorticoid-remediable aldosteronism (GRA) is an autosomal disorder that occur when the promoter region of 11 β-hydroxylase gene (CYP11B1) and the coding regions of the aldosterone synthase (CYP11B2) gene unequally crosses over on chromosome 8q." (PMID 36329155, 2023). "Glucocorticoid remediable aldosteronism (GRA), also known as familial hyperaldosteronism type 1 (FH-I), is a result of the chimeric CYP11B1/CYP11B2 gene, which causes an ectopic expression of aldosterone synthase activity under the regulation of ACTH, resulting in hyperaldosteronism." (PMID 35054115, 2022). "In short, familial hyperaldosteronism type I is attributed to a hybrid Cytochrome P450 Family 11 Subfamily B Member 1 (CYP11B1)/CYP11B2 gene inherited as an autosomal dominant characteristic where aldosterone synthesis is adrenocorticotropic hormone (ACTH)- and not angiotensin II-dependent." (PMID 34771744, 2021).
Cushing syndrome (9 papers, 2015 to 2024). Cushing's syndrome (CS) encompasses a group of hormonal disorders caused by prolonged and high exposure levels to glucocorticoids that can be of either endogenous (adrenal cortex production) or exogenous (iatrogenic) origin. "CYP11B1 plays a crucial role in the biosynthesis of cortisol which can cause a series of diseases known as Cushing’s syndrome." (PMID 25584832, 2015). "Cushing’s syndrome is caused either by excessive medication of cortisol-like compounds or by tumors, such as pituitary and adrenal adenomas, which express high levels of the cortisol synthase gene CYP11B1 and thereby produce a high level of cortisol." (PMID 36982850, 2023). "Cortisol synthase (CYP11B1) is the main enzyme for the endogenous synthesis of cortisol and its inhibition is a potential way for the treatment of diseases associated with increased cortisol levels, such as Cushing's syndrome, metabolic diseases, and delayed wound healing." (PMID 29312923, 2017). "It is reported that 10–20% of patients with APA also have subclinical Cushing’s syndrome, and a relatively high percentage of APAs comprise cells that are double-positive for CYP11B1 and CYP17, which are key enzymes in cortisol biosynthesis." (PMID 35482752, 2022). "Compound 11 was a selective inhibitor of CYP11B1 that is the principal enzyme for the production of cortisol, which inhibition may be a strategy for the treatment of Cushing's syndrome and delayed wound healing." (PMID 29312923, 2017). "The system might additionally be applicable for the screening of CYP11B1 inhibitors, which can be important drugs for the treatment of for example Cushing’s syndrome." (PMID 25880059, 2015). "Therefore, CYP11B1 inhibitors that can be regarded as a pharmacological approach to block cortisol biosynthesis have become another treatment for Cushing’s syndrome." (PMID 25584832, 2015). "Therefore, inhibition of CYP11B1 as the pharmacological approach to block cortisol biosynthesis represents a treatment for Cushing’s syndrome." (PMID 25584832, 2015). "According to previous studies, the heterogeneity of the molecular and gene abnormalities exist in Cushing’s syndrome or subclinical Cushing’s syndrome (SCS), in which epigenetic regulatory mechanisms of CYP11B1 play an important role in cortisol overproduction." (PMID 36982850, 2023). "Whether or not the silencing of CYP11B2 or CYP11B1 using siRNAs can be applied for treating PA or Cushing’s syndrome should be studied." (PMID 36982850, 2023). "Besides, immunohistochemical staining for CYP11B1 and PRKACA analysis did not support the diagnosis of Cushing's syndrome." (PMID 33013693, 2020).
adrenal adenomas (6 papers, 2017 to 2023). "Contrary to the preoperative expectations of pheochromocytomas, all the tumors from the 3 patients who had undergone adrenalectomy were diagnosed with adrenocortical adenomas, which showed positive for CYP11B1 with AMH in the associated adrenal parenchyma." (PMID 35660748, 2022). "The pathological report indicated adrenocortical adenoma, and immunohistochemistry showed diffuse homogeneous expression of CYP11B1 and CYP11B2." (PMID 38017509, 2023). "CYP11B1 were expressed in the bilateral adrenocortical adenomas, and CYP11B2 was also expressed in the right adrenocortical adenomas." (PMID 38017509, 2023). "The pathological report revealed adrenocortical adenoma, the Weiss score was 1, and immunohistochemistry showed weak CYP11B1 expression in the adenoma and positive CYP11B2 expression in an adjacent nodule." (PMID 38017509, 2023). "Despite suspected CA excess in clinical symptoms and imaging findings, the pathological findings of all these tumors were revealed to be cytochrome P450 family 11 subfamily B member 1 (CYP11B1) positive adrenocortical adenomas." (PMID 35660748, 2022). "The right adrenal adenoma showed CYP11B1-negative and CYP11B2-positive staining and harbored the KCNJ5-L168R mutation." (PMID 35399924, 2022).
hypercortisolemia (6 papers, 2017 to 2024). "However, we have noticed that hypermethylation of the CYP11B1 gene and the loss of its expression may be related to the occurrence of hypercortisolemia." (PMID 31354635, 2019). "CYP11B2 hypomethylation in APAs with parallel hypercortisolemia was unchanged; however, these tumors also presented CYP11B1 promoter hypomethylation, especially at two CpG sites near the Ad1/cAMP response element binding site." (PMID 34771744, 2021). "Additionally, the pooled functional method group exhibited lower CYP11B1 scores and less frequent positive hypercortisolism screening results than the anatomical imaging group." (PMID 38051154, 2024). "However, in hypercortisolemia, the role of DNA methylation of 11β-hydroxylase (CYP11B1), which catalyzes cortisol biosynthesis and is highly homologous to CYP11B2, is unclear." (PMID 28894201, 2017). "However, the relationship between CYP11B1 overexpression and DNA methylation in hypercortisolemia has yet to be elucidated." (PMID 28894201, 2017). "In this study, to clarify the molecular mechanism of cortisol production in hypercortisolemia, we examined whether the CYP11B1 expression in CPA was regulated through DNA methylation by carrying out multiple experiments." (PMID 28894201, 2017).
Adrenal insufficiency (5 papers, 2017 to 2025). Insufficient production of steroid hormones (primarily cortisol) by the adrenal glands. "This is different for the potent CYP11B1 inhibitors posaconazole and itraconazole where cases with adrenal insufficiency and hyperplasia have been described, mainly due to cross-reactions with other drugs depending on functional CYP3A4 or in combination with unrelated diseases." (PMID 39175536, 2024). "Our patient did have normal renin and aldosterone levels after developing adrenal insufficiency, likely related to the lower affinity of the osilodrostat for the CYP11B2 enzymatic blockade than for the CYP11B1 enzyme." (PMID 40303510, 2025).
adrenal tumor (5 papers, 2017 to 2024). "Functionality of human adrenal tumors is inferred by CYP11B1 (cortisol synthase) expression, CYP11B2 (aldosterone synthase) expression, or both." (PMID 39387578, 2024). "In cancer, CYP11B1 is not only related to aldosterone- and cortisol-co-secreting adrenal tumors, but it also affects the drug response of breast cancer, gastrointestinal tumors, leukemia, and other tumors." (PMID 33763356, 2021). "The presence of CYP11B1 and CYP17A, the steroidogenic enzymes involved in cortisol production, in adrenal tumor indicate the potential of concomitant autonomous cortisol production." (PMID 34440230, 2021).
familial hyperaldosteronism (5 papers, 2018 to 2024). "The other two forms of familial hyperaldosteronism are attributed to gene rearrangements involving CYP11B1/CYP11B2 (type I familial hyperaldosteronism) and potential alterations at 7p22 (type II familial hyperaldosteronism)." (PMID 29594118, 2018). "We emphasize key differences between CYP11B1 (11β-hydroxylase) and CYP11B2 (aldosterone synthase) and the onset of a hybrid enzyme – CYP11B1/CYP11B2 –, responsible for aldosterone formation in ZF under ACTH control, in “type I familial hyperaldosteronism” (dexamethasone suppressible)." (PMID 35263051, 2022).
adrenocortical carcinoma (4 papers, 2012 to 2023). "For example, CYP11B1 is highly expressed in adrenocortical carcinoma (ACC), which has been reported to be able to differentiate ACC from Cushing Syndrome40." (PMID 37717102, 2023). "The CYP11B1 promoter showed significant activity when a reporter plasmid carrying this promoter region was transfected into human adrenocortical carcinoma H295R cells." (PMID 28894201, 2017).
Hypokalemia (4 papers, 2017 to 2024). An abnormally decreased potassium concentration in the blood. "The real cause of hypokalemia in individuals with PA is due to the fact that the CYP11B1/CYP11B2 hybrid gene is unknown; however, it may be connected to the fact that aldosterone secretion is regulated by ACTH instead of angiotensin II." (PMID 38495792, 2024). "In particular mutations in CYP11B1 and CYP17A1 (encoding for 11β-hydroxylase and 17α-hydroxylase, respectively) are associated with early onset HTN and hypokalemia." (PMID 28587112, 2017).
adrenocortical tumor (3 papers, 2020 to 2021). "Thus, our aim was to analyze the expression profile of four key proteins involved in the steroidogenesis cascade, namely StAR protein, CYP11B1, CYP11B2 and CYP17A1, in different types of adrenocortical tumors." (PMID 32751564, 2020).
autism (3 papers, 2015 to 2019). Persistent deficits in social interaction and communication and interaction as well as a markedly restricted repertoire of activity and interest as well as repetitive patterns of behavior. "Evidence pointing toward the importance of such enzymes was previously found via genetic associations between autism and single-nucleotide polymorphisms in CYP17A1, CYP19A1, and CYP11B1 genes." (PMID 31075898, 2019). "A genetic study of autism found evidence that single nucleotide polymorphisms in sex steroid synthesis genes (ESR2, CYP11B1, CYP17A1, CYP19A1) were associated with autism traits and autism without intellectual disability and good verbal skills." (PMID 30570672, 2019). "Prior evidence pointing toward the importance of such enzymes was previously found via genetic associations between autism and single-nucleotide polymorphisms in CYP17A1, CYP19A1 and CYP11B1 genes." (PMID 24888361, 2015).
hyperaldosteronism (3 papers, 2015 to 2023). Overproduction of aldosterone by the adrenal glands, which may lead to hypokalemia and/or hypernatremia. "We aimed to identify the diagnostic, functional and prognostic value of CYP11B2, CYP11B1, and β-catenin immunostaining in unilateral hyperaldosteronism." (PMID 34631800, 2021). "An unequal crossover event between these genes can result in a gene variant with a CYP11B1 regulatory element and CYP11B2 catalytic sequence, i.e. regulated by ACTH but coding for aldosterone synthase activity, resulting in glucocorticoid-suppressible hyperaldosteronism." (PMID 27293689, 2015).
21-hydroxylase deficiency (2 papers, 2016 to 2025). "Unlike 21-hydroxylase deficiency, molecular-genetic studies of 11β-OHD are relatively fewer, and a number of identified CYP11B1 mutations have not been functionally characterized." (PMID 27316665, 2016).
adrenal Cushing's syndrome (2 papers, 2022 to 2023). "However, the molecular mechanism underlying the CYP11B1 overexpression in adrenal Cushing’s syndrome remains unclear." (PMID 36982850, 2023). "Previous reports have demonstrated the overexpression of CYP11B1 in adrenal Cushing’s syndrome." (PMID 36982850, 2023).
Anxiety (2 papers, 2019 to 2022). Intense feelings of nervousness, tension, or panic often arise in response to interpersonal stresses. "Finally, we assessed the moderating influence of candidate genes whose level of methylation is associated with the Nr3c1 genotype on anxiety-like behavior: Ank3, Avp, Avpr1a, Avpr1b, Bdnf, Cacna1c, Cyp11b1, Cyp11b2, Fkbp5, Hsd11b1, Igf2, Morc1, Nr3c1, Oxt, Oxtr, Pclo, Slc6a4." (PMID 30655507, 2019). "Evidence has showed that long-term high fat diet increases serum corticosterone levels and hippocampal expression of CYP11B1, which elevates HPA activity and then induces anxiety." (PMID 36079775, 2022).
colitis (2 papers, 2019 to 2023). Inflammation of the colon. "In line with the increased activity of LRH‐1 in SHP‐deficient mice, we observed increased colitis‐induced expression of the steroidogenic enzymes Cyp11a1 and Cyp11b1, and associated production of colonic corticosterone." (PMID 36861295, 2023). "Additionally, in a murine model of colitis we confirmed that colitis-induced expression of the steroidogenic enzymes Cyp11a1, Cyp11b1, and Cyp21 is LRH-1-dependent since their induction was significantly reduced in LRH-1 intestine-specific knockout mice." (PMID 31316505, 2019).
melanoma (2 papers, 2020 to 2023). A malignant, usually aggressive tumor composed of atypical, neoplastic melanocytes. "Single-cell transcriptomic data from mouse B16 melanomas revealed that Cyp11b1 was low to undetectable across tumor-infiltrating cell subsets (B cells, dendritic cells, endothelial cells, fibroblasts, macrophages, MAIT cells, neutrophils, NK cells, and T cells)." (PMID 37471141, 2023). "None of the melanoma cell lines were able to convert DOC to corticosterone, indicating an absence of CYP11B1 activity, but all did convert DHC into corticosterone, demonstrating the presence of 11β-HSD1." (PMID 37471141, 2023). "Human melanoma tissues represented a prominent steroidogenic tumor type, expressing CYP11A1, HSD3B1, HSD3B2, CYP17A1, CYP21A1, and CYP11B1 and not expressing CYP11B2." (PMID 32680985, 2020).
metastatic tumor (2 papers, 2016 to 2024). "Of the many APUC genes that have been associated with the activation of AR, we found that 6 (HSD3B1, HSD3B2, CYP11A1, CYP11B1, CYP17A1, and CYP3A43) exhibit robust association in prostate and metastatic tumors and were mutually exclusive with heightened AR activity." (PMID 39207857, 2024). "Six APUC genes (HSD3B1, HSD3B2, CYP3A43, CYP11A1, CYP11B1, CYP17A1) exhibited coalescent gene behavior in a cohort of metastatic tumors (n = 208)." (PMID 39207857, 2024).
Chronic colitis (1 paper, 2023). A chronic inflammatory disease of the large intestine (colon, cecum and rectum). "Along these lines, we have seen that intestine‐specific deletion of Cyp11b1, abrogating intestinal glucocorticoid synthesis, resulted in increased inflammation and increased tumour development during the early phases of chronic colitis." (PMID 36861295, 2023).
colorectal tumours (1 paper, 2023). "In addition, CYP11B1, encoding 11β‐hydroxylase, has been reported to be frequently mutated in different tumours, including colorectal tumours." (PMID 36861295, 2023).
depression (1 paper, 2024). "Genetic polymorphism in the 11β-Hydroxylase gene (CYP11B1) have been also found to be associated with increased risk for late-life depression in women specifically." (PMID 38233401, 2024).
endometrial cancer (1 paper, 2023). Primary or metastatic malignant neoplasm involving the endometrium (mucous membrane that lines the endometrial cavity). "The results showed that SNP sites such as AKR1C2 (rs116900756), AKR1D1 (rs9642092), CYP11B1 (rs1134095), CYP3A7 (rs45446698) appeared simultaneously in the MR analysis results of TT and BioT on ovarian cancer, endometrial cancer, endometriosis, PCOS and POF." (PMID 38075074, 2023).
esophageal cancer (1 paper, 2023). A primary or metastatic malignant neoplasm involving the esophagus. "Importantly, HSD11B1 but not CYP11B1 expression was upregulated in cancer compared with matched healthy control tissues in a range of human tumors including lymphomas (B cell and T cell) and pancreatic, colorectal, stomach, and esophageal cancers." (PMID 37471141, 2023).